ULBP2 (UL16 binding protein 2)
Diseases named in the same sentence as ULBP2 in open-access papers (continued):
Sharing a sentence is not in itself a finding about the gene and the disease.
tumor (99 papers, 2011 to 2025). "It was further demonstrated that treatment of AML cell lines with 5-aza or 5-aza-dC was able to restore transcription of these ligands, of which ULBP2 was the most susceptible to demethylation, resulting in increased NK cell-mediated lysis of tumor cells." (PMID 37090711, 2023). "Reverse transcription-quantitative polymerase chain reaction and immunohistochemistry results showed that ULBP2 was highly expressed in COAD tumor tissues (P < 0.05) and both had diagnostic values (AUC > 0.7)." (PMID 33909599, 2021). "Here, we demonstrate that GSK-3α rather than GSK-3β is the primary isoform restraining the expression of NKG2D ligands, particularly ULBP2/5/6, on tumor cells, thereby regulating their susceptibility to NK cells." (PMID 33918810, 2021). "In both models, anti-CD4 antibody treatment was associated with a trend toward tumor reduction; however, statistical significance was reached only in the mock group, possibly due to inter-animal biological and experimental variability in the ULBP2 group." (PMID 40558520, 2025). "Moreover, the expression levels of ATF3 in CRC correlated with the expression of its target genes, such as CEACAM1, DUSP14, HDC, HLF and ULBP2, which are required for tumor cell invasion and proliferation and are robustly linked to poor prognosis in CRC." (PMID 28402947, 2017). "Anti-CD25 antibody had limited efficacy in mock tumors and tended to promote tumor growth in ULBP2-expressing tumors." (PMID 40558520, 2025). "Mechanistically, ULBP2 overexpression activates the TGF-β signalling pathway, promoting the activation of cancer-associated fibroblasts (CAFs) and tumor progression in GC." (PMID 40775202, 2025). "Soluble ULBP2 derived from tumor cells impairs immune surveillance by inhibiting NKG2D expression and NK cell activity." (PMID 40775202, 2025). "ULBP2 CAR-T cells alone or in combination with PD-1 mAb significantly suppressed tumor growth in MKN-45-ULBP2-T2A-Luc derived CDX models." (PMID 40775202, 2025). "In vitro experiments revealed that sustained exposure to tumor-expressed ULBP2 reduced NKG2D expression and cytotoxic activity of splenocytes." (PMID 40243581, 2025). "Regarding human NKG2D ligands, in vitro studies have reported that tumor cells expressing MICA, MICB, or ULBP2 are more susceptible to NK cell-mediated cytotoxicity." (PMID 40243581, 2025). "ULBP2 and RAET1G (which encodes ULBP5), which share the highest sequence homology with RAET1L, also exhibit similar expression profiles within the tumor microenvironment." (PMID 40116579, 2025). "The anti-tumor effect of ULBP2 CAR-T cells was further significantly enhanced by co-treatment with anti-PD-1." (PMID 40775202, 2025). "We found that ULBP2 CAR-T cells potently curbed tumor growth and prolonged survival compared to un-transduced T cells and anti-PD-1 treatment groups." (PMID 40775202, 2025). "ULBP2 is frequently expressed in tumor cells where it activates natural killer (NK) cells through NKG2D receptor engagement, enabling NK cell-mediated tumor cell cytotoxicity." (PMID 40775202, 2025). "In fact, CD4+CD25+ T cell depletion is known to transiently activate CD8+ T cells, and it is plausible that the interaction between these activated CD8+ T cells and ULBP2-expressing tumor cells was enhanced, resulting in chronic NKG2D stimulation." (PMID 40558520, 2025). "Our findings demonstrated that silencing ULBP2 enhanced cellular sensitivity to radiotherapy and suppressed tumor growth both in vitro and in vivo." (PMID 40640957, 2025). "Targeting ULBP2 suppresses tumor growth, reduces stromal deposition, and promotes T cell infiltration, thereby enhancing the efficacy of immunotherapy in GC." (PMID 40775202, 2025). "These clinical findings suggest that ULBP2 expression on tumor cells suppresses anti-tumor immunity in a clinical context, thereby facilitating tumor progression." (PMID 40243581, 2025).
tumor (continued). "Future studies should include “hot” tumors with robust immune infiltration to better understand how ULBP2 affects the tumor microenvironment." (PMID 40243581, 2025). "In the syngeneic CT26 tumor model, ectopic expression of ULBP2 expressed by tumor cells reduced NKG2D on CD8+ T cells under T cell-modulatory conditions." (PMID 40558520, 2025). "For instance, the SUPRA CAR uses a leucine zipper‐based adaptor system, while convertible CAR employs an inert NKG2D domain that binds to ULBP2‐based adaptors fused to tumor‐targeting antibodies." (PMID 40851786, 2025). "Although membrane-bound ULBP2 drives tumor immunity, some tumors can secrete soluble ULBP2 to evade NK-cell-driven immunosurveillance." (PMID 39672307, 2024). "Research has shown that high tumor expression of NK cell ligands, such as MIC-A/B and ULBP-2, is associated with improved clinical outcomes in various cancers." (PMID 39605908, 2024). "For sULBP2, a clear correlation between tumor staging and grading was observed, suggesting increased cleavage of ULBP2 in T4 tumors or in less differentiated G3 tumors." (PMID 38612935, 2024). "Instead, the authors noted that ULBP2 overexpression correlated with poorer infiltration of CD8+ T cells into tumours, raising the possibility that ULBP2 hindered T cell function via a different (contact-dependent) mechanism." (PMID 37626965, 2023). "In agreement with our studies, previous work from other labs demonstrated cisplatin mediated up-regulation of NK cell cytotoxicity through suppression of AR, and upregulation of ULBP-2 in the HCC tumor model." (PMID 37197660, 2023). "TriKEs targeting the NKG2D receptor ligand ULBP2 (ULBP2/aCD19/aCD19 and ULBP2/aCD19/aCD33 TriKEs) have demonstrated a meaningful in vitro and in vivo anti-tumor activity against CLL." (PMID 35265527, 2022). "ULBP2 protein expression was seen in 79 of 161 (49.1%) COAD patient tumor samples, while ULBP2 was only seen in 3 of 34 (8.8%) adjacent normal tissues." (PMID 33909599, 2021). "The interaction between NKG2D, a receptor of NK cells and cytotoxic T lymphocytes (CTLs), and ULBP2 (NKG2D ligand) expressed in tumor cells, allows NK cells to kill the tumor cells." (PMID 34827646, 2021). "Our results found that ULBP2 expression in COAD tumor tissues was higher than in adjacent normal tissues." (PMID 33909599, 2021). "Up-regulation of stress-induced ligands, including ULBP2, allows tumor cell recognition by immune cells trough the NKG2D receptor expressed on lymphocytes, Natural Killer cells, as well as cytotoxic, CD4 or γδ T cells." (PMID 32604720, 2020). "TriKEs recognizing the NKG2D receptor ligand ULBP2 (ULBP2/aCD19/aCD19 and ULBP2/aCD19/aCD33 TriKEs) have also been used to activate NK cells and showed a superior in vitro and in vivo anti-tumor activity against CLL compared to the bi-specific counterparts." (PMID 33312177, 2020). "ULBP2/5/6 was increased 69% by percent positive among tumor cells (p = 0.04) and 17% by MFI (p = 0.13)." (PMID 32499867, 2020). "The downregulation of miR‐34a/c, which occurs frequently in cancer, leads to an upregulation of ULBP2, thus paradoxically resulting in an increased tumor‐immune surveillance by natural killer (NK) cells." (PMID 30499222, 2019). "The previous experiments showed that VPA induces a significant increase in MICA/B and ULBP-2 surface expression and release from tumor cells of different origin." (PMID 30972064, 2019). "GEM-treated tumour cells were found to express increased amounts of the NKG2D ligands ULBP2 and MICA/B at their surface and microarray analysis suggested this was due to increased transcription induced by GEM treatment." (PMID 30733494, 2019).
tumor (continued). "Killing of MCF10A, MDA-MB-468 and HCC1143 cells by NK cells was indeed reduced after blockage of NKG2D on NK cells using an anti-NKG2D antibody or upon siRNA-mediated knockdown of MICA or ULBP2 in tumor cells." (PMID 28771222, 2017). "Except for HGC27 that mostly expresses MIC A/B (75.1%) but very low positive ratio of ULBP-2 (3.1%), all tumor cells expressed high levels of both molecules." (PMID 26871284, 2016). "As a result, tumor cell lysis was significantly enhanced when B7-H6:HER2-scFv was combined with ULBP2:HER2-scFv relative to lysis obtained with the single agents." (PMID 26392331, 2015). "The upregulation of genes implicated in anti- tumor immune responses was observed, including CCL3 (Chemokine Ligand 3), the Natural Killer cell ligand; ULBP2 and IL24." (PMID 26304929, 2015). "Two ULBP2-expressing tumor cell lines, Jurkat and H9 cells, were cultured to achieve various cell densities by manipulating seeding cell number and/or culture time, and their released ULBP2 in supernatants were determined by ELISA." (PMID 24614922, 2014). "ULBP2 has been shown to shed from tumor cells and exist as a soluble form in sera of tumor patients." (PMID 24614922, 2014). "It is likely that the concentration of ULBP2 from tumor patients results from both spontaneous and apoptosis-induced shedding." (PMID 24614922, 2014). "Our present study and those of others showed that geftinib can partially up-regulate NKG2D ligands ULBP1, ULBP2 or MICA on tumor cells." (PMID 23937717, 2013). "These clinical findings indicate that ULBP2 may promote tumor progression and could represent a potential target for cancer immunotherapy." (PMID 40243581, 2025). "Despite extensive clinical data suggesting its significance, the specific impact of ULBP2 in tumor-bearing animal models with fully competent immune systems remains unclear." (PMID 40243581, 2025). "As B16F10-ULBP2 cells suppressed anti-tumor immunity in a syngeneic subcutaneous transplantation mouse model, we next sought to determine whether surface-expressed or soluble ULBP2 was responsible for this effect." (PMID 40243581, 2025). "To elucidate the role of ULBP2 in immune evasion, we investigated its function in tumor cells." (PMID 40243581, 2025). "While murine tumor cells stably expressing ULBP2 are reportedly rejected upon transplantation into syngeneic mice, the functional role of ULBP2 expressed by tumor cells in transplanted and established tumors in modulating anti-tumor immunity has not been thoroughly investigated." (PMID 40243581, 2025). "Furthermore, recent comprehensive analyses of immune-related genes using the Cancer Genome Atlas dataset revealed that high ULBP2 expression in tumor tissues is one of the top poor prognostic factors in colorectal, head and neck, and breast cancers." (PMID 40243581, 2025). "We further evaluated the anti-tumor efficacy of ULBP2 CAR-T cells using GC organoids." (PMID 40775202, 2025). "Tumor cells secrete soluble ULBP2 to evade NK cells expressing NKG2D." (PMID 39672307, 2024). "SHH MBL, for example, express a range of NKG2DL without great susceptibility to NK cell-mediated tumour clearance, as long as that HLA class I expression is high relative to often-upregulated NKG2DLs such as UL16 binding protein 2 (ULBP-2)." (PMID 37232837, 2023). "Importantly, the protein expression of ULBP2/5/6 was significantly higher in tumor tissues than that in adjacent normal tissues." (PMID 36210637, 2023). "The biological activity of soluble ULBP2 is not well known, but ULBP2 shedding may also inhibit recognition of platelet-tumor aggregates by NKG2D." (PMID 33424862, 2020).
tumor (continued). "In the context of tumor-immunosurveillance, pADAM10 has not only been identified as sheddase of canonical substrates on platelets, but also to be involved in cleavage of the stress-induced NKG2D ligands (NKG2DL) MICA, MICB and ULBP2 from the surface of tumor cells." (PMID 32117229, 2020). "In addition to the direct effects of IL-18 on NK cells, the expression of UL16 binding protein 2, which is a ligand for the NK cell-activating receptor, on tumor cells is increased by exogenous IL-18, leading to the increased NK cell cytotoxicity." (PMID 31731729, 2019). "To find out the key factor that controls spontaneous release of ULBP2 from tumor cells, we set up cell culture experiments to determine the relationship among culture time, seeding cell density, final cell density and concentration of ULBP2 in culture supernatants." (PMID 24614922, 2014). "Therefore, the reduced ULBP2 surface expression on the tumor target in the presence of NK cells suggests a greater rate of shedding than that of spontaneous release." (PMID 24614922, 2014). "Gefitinib could block the immune escape by up-regulating the expression of NKG2D ligands ULBP1, ULBP2 or MICA on tumor cells and NKG2D on NK cells in the co-culture system." (PMID 23937717, 2013). "However, the rapid growth of B16F10-ULBP2 tumors in vivo suggests that prolonged exposure to ULBP2 in the tumor microenvironment may have an opposing effect." (PMID 40243581, 2025). "Additionally, we investigated whether CD8+ or CD4+ T cells contributed to ULBP2-mediated tumor growth." (PMID 40243581, 2025). "However, soluble ULBP2 secreted by tumor cells also contributes to evasion of immunosurveillance." (PMID 33216733, 2020). "Although chemotherapeutic or genotoxic stresses have been implicated in the upregulation of all of the molecules identified as being upregulated by GEM, this investigation may be the first time that a single agent has been shown to increase CD95, TRAILR2, MICA/B and ULBP2/5/6 on tumour cells." (PMID 30733494, 2019). "We demonstrated the efficacy of ULBP2 CAR-T cells alone, and particularly in combination with PD-1 blockade, to inhibit tumor growth and promote survival, using GC cell lines and organoids, as well as CDX and PDX models." (PMID 40775202, 2025). "ULBP2, like MICA and MICB, is a human NKG2D ligand, and its ectopic expression in murine tumor cells carries the potential for immune rejection due to its xenogeneic nature." (PMID 40243581, 2025). "In the same model, we also found that CD4+ T cell depletion significantly reduced tumor growth in mice bearing mock-transfected B16F10 tumors; however, this effect was lost in mice bearing ULBP2-expressing tumors." (PMID 40558520, 2025). "The combination of ULBP2 CAR-T cells and anti-PD-1 mAb significantly inhibits tumor growth and improves survival in preclinical models." (PMID 40775202, 2025). "ULBP2 and MICA/B are predominantly expressed on tumor cell surfaces and can be shed into extracellular fluids via proteolytic cleavage by proteases of the ADAM family." (PMID 40558520, 2025). "UL16-binding protein 2 (ULBP2), a ligand for the activating receptor NKG2D, plays a dual role in tumor immunity, promoting immune activation or suppression, depending on the context." (PMID 40558520, 2025). "For example, IMP3 suppressed the NKG2D ligand UL16-binding protein 2 (ULBP2) and indirectly downregulated MHC class I polypeptide-related sequence B (MICB), which facilitated tumour immune evasion." (PMID 39718205, 2025). "Enhances tumor immunogenicity by increasing immune ligands (MHC I, MICA/B, ULBP2/5/6) on cancer cells, promotes cytotoxic T cell and NK cell activation; supports immune clearance of tumors." (PMID 39949780, 2025). "Studies have reported that soluble ULBP2, as a ligand of NKG2D, suppresses the expression of NKG2D and inhibits NK cell activity, thereby allowing tumor cells to escape immune surveillance and promoting immune evasion." (PMID 40496857, 2025).
tumor (continued). "In tumor cells, ligands of ULBP1, ULBP2/5/6, ULBP3, ULBP4, and MICA/B can bind to NKG2D receptors among tumor-activating receptors of NK cells." (PMID 39339179, 2024). "We examined the surface expression of MICA/B, ULBP1, ULBP2/5/6 and ULBP3 on SKOV-3, BT-474 and MCF-7 tumor cells growing in 3D culture after spheroid dissociation." (PMID 39457710, 2024). "Tumor cells and primary MM cells treated with DRd for 24 h showed significantly increased expression of MICA, MICB, ULBP1, ULBP2, and Fas receptor compared to Rd or untreated tumor cells (all p < 0.0001)." (PMID 36385211, 2023). "Tumor-derived EVs also express the surface ligands of NKG2D, such as ULBP-2 and MICA/MICB, acting as negative regulators of NKG2D on NK cells in a dose-dependent manner and impairing cytotoxicity against tumor cells." (PMID 37175226, 2023). "We found the mRNA expression level of MICA, MICB, ULBP1, ULBP2, ULBP4, and ULBP5 was significantly higher in tumor tissues than that in adjacent normal tissues, whereas ULBP3 expression was lower in tumor tissues compared to adjacent normal tissues." (PMID 36210637, 2023). "In fact, the interaction between the NKG2D receptor of natural killer (NK) cells with cytotoxic T lymphocytes (CTLs), and UL16 binding protein 2 (ULBP2), which is an NKG2D ligand expressed in tumor cells, allows NK cells to kill the tumor cells." (PMID 37175874, 2023). "miR-34a functions as a repressor of ULBP2 by directly targeting its 3′-UTR, resulting in the repression of NKG2D-mediated immune surveillance in melanoma and enhanced tumor progression." (PMID 33763422, 2021). "Our differential expression analysis results showed that ULBP1, ULBP2, ULBP3, and RAET1L had significant differential expression in COAD tumor and adjacent normal tissues." (PMID 33909599, 2021). "MicroRNAs miR‐34a/c and miR‐499a/c bind to the 3′‐UTR of ULBP2, a ligand of NKG2D receptor that activates NK cells against the tumor." (PMID 30499222, 2019). "Gefitinib can upregulate the expression of ULBP1, ULBP2, and MICA in tumor cells and can promote the expression of NKG2D in NK cells, thereby inhibiting tumor escape." (PMID 30813924, 2019). "The ULBP2 gene is a known ligand of the activating NK receptor NKG2D, and it is critically involved in tumor immunosurveillance." (PMID 28402947, 2017). "NKG2D ligands, ULBP1, ULBP2, MICA, and MHC-I on tumor cells, and NKG2D, NKp44 and NKp46 on NK cells were evaluated with flow cytometry." (PMID 23937717, 2013). "Strong expression of Vδ1+ T cell target NKG2D ligands (NKG2DL) ULBP-2 and ULBP-3 and moderate expression of ULBP-1 was noted on both tumor cell lines." (PMID 23950874, 2013). "The HTB-186 tumor cell line expressed the highest levels of HLA class I, MICA, ULBP-2, ULBP-3 and the lowest NKG2DLs/HLA class I ratio." (PMID 23626949, 2013). "Formalin-fixed paraffin-embedded tumor tissue was immunohistochemically stained with antibodies directed against MIC-A/MIC-B (MIC-AB), ULBP-1, ULBP-2, ULBP-3, ULBP-4, and ULBP-5." (PMID 22257486, 2012). "When the average tumor size reached 90 mm3, CDX mice were infused with ULBP2 CAR-T cells." (PMID 40775202, 2025). "Anti-CD4 antibody significantly suppressed tumor growth in mock-transfected tumors, while no significant suppression was observed in ULBP2-expressing tumors." (PMID 40558520, 2025). "IHC staining revealed a significant increase in the number of CD8+ T cells in the ULBP2 CAR-T cell-treated mice compared with that in the control mice, and co-treatment with anti-PD-1 further enhanced the infiltration of cytotoxic T cells into the tumor." (PMID 40775202, 2025). "Furthermore, we demonstrated that ULBP2 expressed on the tumor cell surface, suppressed NKG2D-mediated anti-tumor immunity, promoting tumor growth." (PMID 40243581, 2025). "The observation that cell surface-expressed ULBP2, a ligand for the activating receptor NKG2D, suppresses anti-tumor immunity may initially seem contradictory to earlier reports." (PMID 40243581, 2025).